POMK (protein O-mannose kinase)
Description:
Protein O-mannose kinase that specifically mediates phosphorylation at the 6-position of an O-mannose of the trisaccharide (N-acetylgalactosamine (GalNAc)-beta-1,3-N-acetylglucosamine (GlcNAc)- beta-1,4-mannose) to generate phosphorylated O-mannosyl trisaccharide (N-acetylgalactosamine-beta-1,3-N-acetylglucosamine-beta-1,4- (phosphate-6-)mannose). Phosphorylated O-mannosyl trisaccharide is a carbohydrate structure present in alpha-dystroglycan (DAG1), which is required for binding laminin G-like domain-containing extracellular proteins with high affinity. Only shows kinase activity when the GalNAc-beta-3-GlcNAc-beta-terminus is linked to the 4-position of O-mannose, suggesting that this disaccharide serves as the substrate recognition motif.
Synonyms: SGK196; FLJ23356; MDDGA12; MDDGC12
Tractability: Antibody: UniProt predicts a signal peptide or a membrane-spanning region. PROTAC: ubiquitination databases record sites on it; its protein half-life has been measured.
Gene: Protein-coding gene on chromosome 8 (43,093,498 to 43,131,180, forward strand). Ensembl gene ENSG00000185900.
Subcellular location: Endoplasmic reticulum membrane
Pathways (Reactome):
Metabolism of proteins: DAG1 core M3 glycosylations
Gene Ontology:
Molecular function: phosphotransferase activity, alcohol group as acceptor; protein binding; carbohydrate kinase activity; mannokinase activity; ATP binding; protein kinase activity
Biological process: carbohydrate phosphorylation; protein O-linked glycosylation; brain development
Cellular component: endoplasmic reticulum membrane
Genetic constraint (gnomAD): Loss-of-function variants: 22 observed, 27.99 expected, observed/expected ratio (o/e) 0.79, 90% interval 0.56 to 1.12. The upper end of that interval is the gene's LOEUF score, 1.12, which puts it in group 4 of 6, group 1 being the genes least tolerant of losing a copy. Missense variants: 410 observed, 454.01 expected, observed/expected ratio (o/e) 0.9, 90% interval 0.83 to 0.98. Synonymous variants: 173 observed, 182.12 expected, observed/expected ratio (o/e) 0.95, 90% interval 0.84 to 1.08.
Homologues: Orthologues: chimpanzee POMK (99% identical), dog POMK (83% identical), rabbit POMK (83% identical), mouse Pomk (81% identical), pig POMK (80% identical), rat Pomk (79% identical), guinea pig POMK (78% identical), tropical clawed frog pomk (59% identical), zebrafish pomk (52% identical).
Diseases named in the same sentence as POMK in open-access papers:
POMK is named in the same sentence as 15 diseases in open-access papers, as found by Europe PMC text mining. Sharing a sentence is not in itself a finding about the gene and the disease. The quoted sentences say what the papers report.
dystroglycanopathies (8 papers, 2015 to 2024). "POMK has an ER-related function in phosphorylating glycosylation-specific O-mannose and is mutated in a neuromuscular disorder dystroglycanopathies." (PMID 33988507, 2021). "Bi-allelic pathogenic variants in POMK are the cause of a broad spectrum of alpha-dystroglycanopathies." (PMID 32907597, 2020). "POMK mutations cause not only Walker–Warburg syndrome but also a more severe subtype, type C12 (MDDGC12) limb-girdle muscular dystrophy-dystroglycanopathy and type A12 (MDDGA12) congenital muscular dystrophy-dystroglycanopathy with brain and eye anomalies." (PMID 36825005, 2023). "Interestingly, unlike with other dystroglycanopathy genes there are patients with complete loss-of-function mutations in POMK who suffer from mild forms of dystroglycanopathy, suggesting some expression of matriglycan without POMK." (PMID 32975514, 2020). "This short matriglycan likely attenuates muscular dystrophy in patient NH13-284 with a complete loss-of-function mutation in POMK, preventing the severe WWS phenotype that is observed in the complete absence of the other known dystroglycanopathy genes." (PMID 32975514, 2020).
congenital muscular dystrophy (4 papers, 2016 to 2023). A muscular dystrophy that is characterized by diminished muscle tone (hypotonia), progressive muscle weakness and degeneration (atrophy), abnormally fixed joints, spinal rigidity, and delays in reaching motor milestones such as sitting or standing unassisted. "Finally, it is interesting to note that some patients with a POMK Q109* mutation presented with a limb-girdle muscle dystrophy, while others presented with a more severe congenital muscular dystrophy." (PMID 27879205, 2016).
muscular dystrophy (4 papers, 2016 to 2022). Muscular dystrophy (MD) refers to a group of more than 30 genetic diseases characterized by progressive weakness and degeneration of the skeletal muscles that control movement. "Our study provides mechanistic insights into a unique ‘pseudokinase’ and a deeper understanding of the molecular mechanisms that underlie the pathogenesis of muscular dystrophy caused by POMK mutations." (PMID 27879205, 2016). "It is suspected that POMK plays an important role in the fetal development of myocytes, and indeed, embryonic pomk knockout zebrafish showed reduced embryonic motility and muscular dystrophy 3 days post fertilization." (PMID 32907597, 2020). "POMK is a novel muscular dystrophy gene that phosphorylates mannose of the core M3 trisaccharide (GalNAc-β1,3-GlcNAc-β1,4-Man) on α-DG during synthesis of the O-mannose-linked polysaccharide ending in matriglycan." (PMID 32975514, 2020). "Collectively, our study demonstrates that phosphorylation of core M3 by POMK enables LARGE1 to elongate matriglycan on α-DG, thereby preventing muscular dystrophy." (PMID 32975514, 2020). "Muscle-specific POMK KO mice express the short, non-extended form of matriglycan on ~90 kDa α-DG and develop a mild muscular dystrophy phenotype." (PMID 32975514, 2020).
breast carcinoma (3 papers, 2020 to 2022). "It was determined, however, that in basal-type breast cancer (BLBC) POMK is only present in its N-glycosylated form, its overexpression being related with a better relapse-free survival from this subtype of tumor." (PMID 36494657, 2022). "In breast cancer (BRCA), overexpression of six dark kinases is associated with decreased overall survival (ALPK3, CSNK1A1L, CSNK2A3, NRK, POMK, and PSKH1)." (PMID 33205077, 2020). "Overexpression of this gene at the protein level has also been detected in breast cancer by immunohistochemistry, with POMK being found both N-glycosylated (in a process regulated by ribophorin 1, or RPN1) and lacking N-glycosylation in both tumor and healthy tissues." (PMID 36494657, 2022).
limb-girdle muscular dystrophies (2 papers, 2016 to 2023). "Mutations of POMK lead to a spectrum of congenital disorders of glycosylation and limb-girdle muscular dystrophies by influencing the biosynthesis of functional alpha-dystroglycan." (PMID 36825005, 2023). "POMK mutations cause a spectrum of congenital and limb-girdle muscular dystrophies, including the most severe presentation known as the Walker-Warburg syndrome, which is associated with brain and eye abnormalities and death in early childhood." (PMID 27879205, 2016). "Multiple mutations in POMK cause congenital or limb-girdle muscular dystrophy in humans." (PMID 27879205, 2016).
meningoencephalocele (1 paper, 2020). A congenital abnormality in which the meninges protrude through a defect in the cranium. "Our combined data suggest a more important role for POMK in the pathogenesis of meningoencephalocele." (PMID 32907597, 2020). "Our combined clinical and genetic findings thus expand the clinical spectrum of POMK patients and classify POMK as candidate gene for meningoencephalocele." (PMID 32907597, 2020).
Stillbirth (1 paper, 2024). Death of the fetus in utero after at least 22 weeks of gestation. "To date, only nine pathogenic POMK variants have been reported worldwide in 16 cases, and five of them were stillbirth or fetuses from induced termination of pregnancy." (PMID 38296890, 2024).
tumor (2 papers, 2020 to 2022). "On the other hand, a series of other genes acting earlier in this pathway are overexpressed in tumor cells, namely DOLK, DPM1/2/3, POMGNT1, B3GALNT2, POMK and FKTN, hence exerting instead a pro-oncogenic role." (PMID 36494657, 2022).
POMK also shares sentences with these, for which no sentence is quoted: Walker-Warburg syndrome (3 papers); brain malformations (2); cancer (1); Cognitive impairment (1); Hydrocephalus (1); mental retardation (1); Ventriculomegaly (1).